CD4 (CD4 molecule)
Diseases named in the same sentence as CD4 in open-access papers (continued):
Sharing a sentence is not in itself a finding about the gene and the disease.
atherosclerosis (continued). "We tested whether activation T cells explained the increased atherosclerosis in Cd47−/− mice by antibody depletion of CD4+ and CD8+ T cells." (PMID 31337788, 2019). "Adoptive transfer of B cells deficient in either MHCII or co-stimulatory molecule CD40, molecules required for B and CD4 T cell interaction, into B cell-deficient μMT−/− ApoE−/− mice failed to increase atherosclerosis." (PMID 31998318, 2019). "In addition, disruption of TGF-β signaling in CD4+ T cells of ApoE−/− mice promotes atherosclerosis by enhancing the Th1 response." (PMID 31653058, 2019). "Thus, mitochondrial STAT3 can sustain prolonged cytokine production and contribute to the differentiation of CD4+ T cells in atherosclerosis." (PMID 31588227, 2019). "Finally, effector memory T cells, including CD4+ Th1 and CD8+ TC, were associated with increased atherosclerosis and CAD." (PMID 30064449, 2018). "It plays a key role in the immune response and may be involved in the occurrence and development of atherosclerosis by regulating CD4+ T lymphocytes, monocytes/macrophages, endothelial cells, and vascular smooth muscle cells." (PMID 30046360, 2018). "The polarization of DCs and CD4+ T cells is critical for the development of atherosclerosis." (PMID 28607385, 2017). "In line with above finding, our results showed that chronic METH could induce the transformation of CD4+ T cells to Th1 cells, this finding might thus be responsible for the observed enhanced atherosclerosis in this model." (PMID 28903402, 2017). "Our results indicate that METH might enhance the progress of atherosclerosis by affecting the changes of CD4+ T cells subsets in the high cholesterol diet circumference in APOE−/− mice." (PMID 28903402, 2017). "Low nadir CD4+ T lymphocyte count and ongoing HIV replication are linked to chronic immune activation and inflammation in HIV-infected persons, contributing to atherosclerosis development via HIV-mediated endothelial injury and the promotion of a pro-thrombotic state." (PMID 27503230, 2016). "Our results show that the immune system cell types involved in regulatory mechanisms may be over stimulated in the early pre-clinical phase of atherosclerosis and that a relationship exists between CD4 + CD25highFoxP3+ frequency and circulating lipids." (PMID 26822994, 2016). "Here, we summarize recent advances on the role of CD4+ T cells in the inflammatory process in atherosclerosis and discuss potential therapies to modulate these lymphocytes that may provide future breakthroughs in the treatment of atherosclerosis." (PMID 27418972, 2016). "In addition to Th1, Th2, and Th17 lineage, regulatory T cells (Tregs), a special subset of CD4+ T cells, inhibit atherosclerosis development by attenuating activated T cell responses." (PMID 26663989, 2015). "In the SMART study, a study aimed to investigate the benefit of a CD4 guided approach on treatment, markers of inflammation and coagulation such as IL-6, D-dimer and sCD14 were shown to be excellent predictors of atherosclerosis and mortality." (PMID 25814984, 2015). "Hence, these findings have showed that CD4+ T cell subpopulations play an important role in the initiation and progression of atherosclerosis." (PMID 26663989, 2015). "Moreover, the importance of T cells in atherogenesis has been highlighted by animal studies showing that transfer of CD4+ T cells aggravates, whilst depletion of CD4+ T cells attenuates atherosclerosis in apoE-/- mice." (PMID 25253303, 2014). "After signal activation, CD4+ T cells could migrate into atherosclerotic plaque and affect the development of atherosclerosis." (PMID 24743945, 2014).
atherosclerosis (continued). "Indeed transfer of CD4+ T cells to immunodeficient mice have been reported to aggravate atherosclerosis development." (PMID 23560095, 2013). "Accumulating evidence has shown that CD4+ effector T (Teff) cells may accelerate atherosclerosis development." (PMID 24385687, 2013). "The existence of atherosclerosis-related CD4+ T-cell epitopes is suggested by several experiments." (PMID 24416033, 2013). "In contrast, CD4+ regulatory T (Treg) cells play a protective role in atherosclerosis." (PMID 24385687, 2013). "Recently, the role of CD4+LAP+ Treg cells in atherosclerosis has been extensively investigated." (PMID 24385687, 2013). "Conventional B-2 B cells can promote atherosclerosis through less clearly defined mechanism that may involve CD4 T cells." (PMID 23248624, 2012). "The induction of regulatory CD4+ T cells is anti-atherogenic while depletion leads to increased lesion development, highlighting the dual role of CD4+ T cells and that imbalance may accelerate atherosclerosis." (PMID 22479479, 2012). "Expansion of CD4+CD28null T cells in these patients may contribute to the progression of atherosclerosis." (PMID 16207339, 2005). "Furthermore, CD4+ T cells aggravate atherosclerosis in established mouse models." (PMID 40139879, 2025). "Therefore, targeting specific CD4+ and/or CD8+ T cell populations could offer potential therapeutic strategies to modulate immune responses, attenuate inflammation, and mitigate atherosclerosis progression and associated cardiovascular risks." (PMID 39940640, 2025). "However, increased expression of Tregs artificially alleviated atherosclerosis, and depletion of CD4+ Tregs accelerated atherosclerosis, implying that Tregs could still control the progression of atherosclerosis." (PMID 41143276, 2025). "Given our recent report showing the augmented immune responses related to Th1, Th2, and Th17 cells in CD4+Foxp3+ Treg-depleted atherosclerosis-prone mice, augmentation of these helper T cell responses may be caused by dysregulated CD4+Foxp3+ Treg responses in our Ccr4-/-Apoe-/- mice." (PMID 40608058, 2025). "The detection of IL-17A-producing CD4+ T-cells in the atherosclerotic plaques of mice supports the possibility that subsets of Th17 cells may be recruited into the vascular beds and locally fuel atherosclerosis." (PMID 38247848, 2024). "Therefore, the number and activity of naive CD4+ T cells may be related to the development of atherosclerosis and coronary artery disease." (PMID 39610972, 2024). "Therefore, fatty acid-mediated metabolic reprogramming of CD4+ T cells may affect the initiation and progression of atherosclerosis by skewing CD4+ T cells toward a pro- or anti-inflammatory phenotype." (PMID 38558932, 2024). "Aberrant infiltration of CD4+ and CD8+ T cells in the vascular wall is closely associated with the formation of atherosclerotic lesions, which contribute to monopoiesis and macrophage accumulation as well as necrotic core formation in the early stages of atherosclerosis." (PMID 37297017, 2023). "A total of 9 modules were obtained from the atherosclerosis sample, and the highest positive correlations were selected from the turquoise and Macrophages M0 modules, and the highest negative correlations were selected from the turquoise and T cells CD4 memory resting modules." (PMID 37369700, 2023). "In addition to the activation and expansion of Tregs, we found HCW9302 also expanded the percentage of NK cells and reduced levels of CD4+ T cells in the blood and expanded M2 macrophage and MDSC levels in the atherosclerosis plaques of WD-fed ApoE deficient mice." (PMID 36761778, 2023). "Interestingly, in late-stage atherosclerosis, three major T cell subsets appear to undergo clonal expansion, indicating that generation of autoreactive CD4, CD8, and Treg cells may play an important role in ASCVD progression." (PMID 38213548, 2023).
atherosclerosis (continued). "The T helper cell (Th1) is a prevalent type of CD4 T cell that induces macrophage activation and increases inflammatory Th1 cells mostly by secreting interferon, an indispensable pro-inflammatory cytokine that is created in human atherosclerotic lesions and hastens atherosclerosis in mice." (PMID 35269559, 2022). "In summary, IL-7 had a dual effect on coronary atherosclerotic disease, which could promote the formation of atherosclerosis by activating monocytes/macrophages and platelets, etc., and could also upregulate the level of Tim-3 in CD4+ T cells in peripheral blood of patients with CHD." (PMID 34236813, 2022). "Stimulated CD4+ T lymphocytes can differentiate into effector T-cell (Teff) or regulatory T-cell (Treg) subsets; Teff responses promote atherosclerotic disease, while Tregs have been shown to induce the regression of atherosclerosis and increase plaque stability." (PMID 36286310, 2022). "To note, more than half of CD4+ T cells reactive to ApoB peptides express FoxP3 in individuals without cardiovascular disease but dramatically decrease and acquire the expression of RORγt and T-bet transcription factors in patients with subclinical atherosclerosis." (PMID 35966516, 2022). "Overall, these data suggest that PD-1/PD-L1 axis has an important role in downregulating atherosclerosis by limiting APC-dependent T-cell activation, and that PD-1/PD-L1 blockade may contribute to atherosclerosis progression in murine models through increased activation of CD4+ and CD8+ T-cells." (PMID 34124192, 2021). "In HIV-infected patients, despite a low SCORE index, if they had a high zenith VL and a low current nadir or CD4 cell concentration, diagnostic tests (IMT or coronary artery calcium score) could be indicated for the diagnosis of subclinical atherosclerosis, which would allow primary prevention." (PMID 34531450, 2021). "In hyperlipidemic conditions, CD4+ T cells are activated and produce inflammatory cytokines, especially IL-17, in the aorta, blood, spleen, and bone marrow, which induces the migration of macrophages and neutrophils to atherosclerotic lesions and exacerbates the development of atherosclerosis." (PMID 33981738, 2021). "Furthermore, pDC-specific deletion of MHCII molecules also reduced the development of atherosclerosis via defective activation of antigen specific CD4+T cells, accompanied by a marked reduction of the T cell-produced inflammatory cytokine IFN-γ and T cell migration into the lesion." (PMID 32849502, 2020). "In addition to antigen presentation to CD4 T cell, B cells can potentially aggravate atherosclerosis by at least two other mechanisms, namely the production of atherogenic IgG and the secretion of pro-inflammatory cytokines, including TNFα, which are T cell-independent pathways." (PMID 31206525, 2019). "Interaction between B and CD4 T cells may be important in atherosclerosis pathogenesis and targeting B and CD4 T cell interaction may be important therapeutic target to limit arterial inflammation in atherosclerosis." (PMID 31998318, 2019). "On the other hand, deranged balance of CD4 + T cell subsets whose lineage commitment is specified by cytokine environment and activation of their corresponding transcription factors might also promote atherosclerosis." (PMID 31299986, 2019). "When LT-ApoE−/− mice were fed a western diet for 15 weeks, we observed an increase in the number of CD4+ T cells in the aorta and most of these cells were activated, CD62Llo cells, suggesting that in our mouse model there is CD4 T cell participation during atherosclerosis development." (PMID 29545616, 2018).
atherosclerosis (continued). "Indeed, CD4+CD28− T cells were reported to be a major T cell subset observed among infiltrating cells at sites of inflammation and were found to be associated with atherosclerosis, suggesting that CD4+CD28− T cells take part in vascular plaque destabilization." (PMID 28596556, 2017). "The results indicate that PP5 increases expression of methylation sensitive T cell genes, and may contribute to the aberrant gene expression in CD4+CD28+ T cells that characterize lupus flares as well as the aberrant gene expression in CD4+CD28− T cells that promote atherosclerosis." (PMID 28239687, 2016). "As opposed to direct contributions of CD4+ T cells towards atherosclerosis, associations of chronic CD4+ T cell activation with atherosclerosis may reflect persistent immune activation and inflammation resultant from chronic pathogenic burden." (PMID 24009662, 2013). "Moreover, to check whether Th17 cells could develop into IL-22 producing Th17 cells in the local inflammation environment of atherosclerosis, we analyzed CD4+IFN-γ−IL-17+IL-22+ cells separately." (PMID 24312440, 2013). "Also in genetically CCR5 deficient mice with diet induced atherosclerosis, reduced lesion size, increased IL-10 and decreased TNF-α production by CD4+ and CD8+ T cells, and reduced macrophage accumulation in plaques and lowered circulating IL-6 levels was seen." (PMID 22348061, 2012). "This persistent immune activation may have important clinical consequences; for example, persistent T cell activation is associated with lower CD4 cell count increases in patients receiving ART and may contribute to accelerated atherosclerosis or premature immunosenescence." (PMID 20711481, 2010). "Therefore, the study of CD4+ T cells is a promising route to further understanding ASCVD, and investigating how EPA can influence these cells can indicate a potential mechanism underlying the beneficial effects of EPA on atherosclerosis." (PMID 40139879, 2025). "At the same time, T cells, especially CD4+ and CD8+ T cells, also play important roles in atherosclerosis." (PMID 40894479, 2025). "Among the T-cell subtypes, CD4 Th1 T-cells and CD8 T-cells appear to promote atherosclerosis, whereas Th2 T-cells exert protective effects." (PMID 40218153, 2025). "In a mouse model of atherosclerosis, blocking TIM-3 reduced lesion size and increased monocyte and CD4+ T cell frequencies." (PMID 40761788, 2025). "Gene network analysis using the STRING database of the top 100 downregulated genes predicted novel interactions among genes such as CD4 and Beclin1 as well as CTSS, which is known to be impaired in atherosclerosis." (PMID 39120300, 2024). "CD4+ T cells produce pro-inflammatory cytokines like IFN-γ and IL-17, contributing to endothelial dysfunction and atherosclerosis." (PMID 39000373, 2024). "We believe that CD4+ and CD8+ T cells play an important role in inflammation, which is a core pathological process in atherosclerosis." (PMID 39161605, 2024). "Targeting CD4+ T‐cell activation and CX3CR1+ polarization has the potential to attenuate atherosclerosis in PD patients." (PMID 38979792, 2024). "Remarkably, a clear overlap between PBMCs from atherosclerosis and PSA was observed in both CD4+ and CD8+ T cells." (PMID 38665903, 2023). "Human-activated CD4+ T cells released sEV that induced cholesterol accumulation and TNF-α production on monocytes, suggesting a detrimental effect of sEV in the atherosclerosis setting." (PMID 37762077, 2023). "In contrast to CD4+ T cells, the role of CD8+ (cytotoxic) T cells in atherosclerosis is less well-understood." (PMID 37356205, 2023). "The literature has little to say about CCR4 and atherosclerosis clinically, with only one brief report that described a positive correlation between CCR4 expressing CD4 T cells and Gensini score in a population of patients undergoing invasive angiography." (PMID 37927302, 2023).
atherosclerosis (continued). "Next, clonal expansion levels were recalculated for both atherosclerosis and PSA (percentage of all CD4+ or CD8+ TCRs)." (PMID 38665903, 2023). "At various stages of atherosclerosis, pro-inflammatory CD8+ and CD4+ T cells, as well as natural killer (NK) cells, can be involved in the process, and their migration can be facilitated by the soluble form of SR-G1 secreted by Mf (chemokine CXCL16)." (PMID 37175617, 2023). "FOSB was upregulated in plaque only, similarly to CD4+ C3, and JUNB expression was increased in PSA compared to atherosclerosis." (PMID 38665903, 2023). "In CVD such as atherosclerosis, CD4+ and CD8+ memory T cells contribute to endothelial vascular dysfunction and the progression of atherosclerosis." (PMID 36560733, 2022). "Inhibition of T-cell autophagy reduced the number of CD4+, CD8+ and NKT cells, perhaps reducing atherosclerosis." (PMID 35402552, 2022). "Since P210-PAM immunization elicited an antigen-specific regulation of CD4+ and CD8+ T cells, we next tested if such regulation involved the IL-1β signaling pathway given the known involvement of this pathway in atherosclerosis." (PMID 35536648, 2022). "Complete CD4+ or CD8+ T cell ablation reduces atherosclerosis, suggesting that T cells in plaques are mainly pro-atherogenic." (PMID 35778407, 2022). "Furthermore, low levels of lymphocytes could be associated with atherosclerosis because of the lack of neuroprotective effect of CD4 T cells." (PMID 34442341, 2021). "Inflammatory myeloid cells as well as CD4+ and CD8+ T cell activation are hallmarks of atherosclerosis." (PMID 34425108, 2021). "CD4+CD25+Foxp3+ Treg exerts immunomodulatory effects by releasing anti-inflammatory cytokines IL-10 and TGF-β to inhibit the development of atherosclerosis possibly through promoting the conversion of M1 to M2 macrophages." (PMID 34901005, 2021). "These CD4+ CD28null cells express higher levels of pro-inflammatory and cytotoxic mediator than CD4+ CD28+ cells, strengthening their role in mediating the early development of atherosclerosis." (PMID 34680058, 2021). "Moreover, resting CD4 memory T cells, T cells follicular helper, M0 and M2 macrophages showed a different infiltration percentage between stable and unstable atherosclerotic plaques, which could be an immunotherapy target for atherosclerosis." (PMID 34729909, 2021). "This was likely antigen-driven, since hypercholesterolemia increased T-cell receptor (TCR) signaling and proliferation in CD4+ T cells, supporting the role of LDL or its major protein component apolipoproteinB100 (apoB100) as autoantigens in atherosclerosis." (PMID 35087883, 2021). "Conversely, in vivo supplementation with purified spleen CD4+CD25+ Tregs or IL-10-producing Tr1-like Tregs reduced atherosclerosis in Apoe−/− mice and induced a more stable plaque phenotype." (PMID 33805071, 2021). "Effector T cell function that exacerbates atherosclerosis is attributed in part to IFN-γ, which concur with our observation that COL6A1 immunized male mice had increased CD4+ EM T cells and CD4+IFN-γ+ T cells." (PMID 32373127, 2020). "Several human and murine studies already demonstrated accelerated immune processes after blocking or depleting PD-1 or its ligand PD-L1, with parallel increased lesional CD4+ and CD8+ T cell levels in atherosclerosis." (PMID 33383733, 2020). "Our study demonstrates that interaction between B and CD4 T cells utilizing MHCII and CD40 is essential to augment their function to increase atherosclerosis in hyperlipidemic mice." (PMID 31998318, 2019). "We found compelling evidence that B cells interact with CD4 T cells using MHCII and CD40 molecules to increase atherosclerosis development." (PMID 31998318, 2019).